CXCR1 (C-X-C motif chemokine receptor 1)
Diseases named in the same sentence as CXCR1 in open-access papers (continued):
Sharing a sentence is not in itself a finding about the gene and the disease.
colorectal cancer (14 papers, 2018 to 2025). A primary or metastatic malignant neoplasm that affects the colon or rectum. "CXCL8 and its receptors (CXCR1, CXCR2, and Duffy antigen receptor for chemokines (DARC)) are associated with the development of colorectal cancer and its liver metastases." (PMID 37142825, 2024). "The inhibition of CXCR1/2 limits neutrophil infiltration and results in the decreased growth of multiple tumors, including lung adenocarcinoma, colorectal cancer, and pancreatic ductal adenocarcinoma." (PMID 36091114, 2022). "In colorectal cancer cells, miR-215-3p improves the 5-Fu sensibility of cancer cells via regulating CXCR1 expression." (PMID 34516330, 2021). "CXCR1 showed a minimal impact on survival (HR = 1.04, 95% CI: 0.83–1.31), which aligns with studies such as, which also found no strong association between CXCR1 expression and colorectal cancer patient survival." (PMID 41024311, 2025). "MiR-215-3p by targeting CXCR1 could improve the 5-Fu sensibility in the colorectal cancer cell." (PMID 33954114, 2021). "CXCL8 is secreted by monocytes and macrophages, which exerts potent angiogenic properties on endothelial cells through interaction with CXCL8 receptors CXCR1 and CXCR2 for regulating angiogenesis in colorectal cancer." (PMID 34025668, 2021).
gastric cancer (14 papers, 2013 to 2025). A primary or metastatic malignant neoplasm involving the stomach. "Among them, Reparixin, a small molecular antagonist against CXCR1/2, has been intensively studied for its great potential for multiple cancer treatments, including colorectal, breast, and gastric cancers 42-46." (PMID 39897048, 2025). "PPBP and its chemokine CXCL7 influence tumor biology via CXCR1/2 binding and were proposed as early lung and gastric cancer biomarkers." (PMID 40297587, 2025). "Recently, macrophages were identified to secrete CXCL8 under hypoxic conditions, which hyperactivated the JAK-STAT1 pathway in gastric cancer by interacting with C-X-C motif chemokine receptor 1/2 (CXCR1/2) on the cell membrane." (PMID 38273295, 2024). "Protein–protein interaction and co-expression analysis showed a strong association of CXCL1 with CXCR1, CXCR2, IL6, and IL1B in human gastric cancer tissue samples." (PMID 36614235, 2023). "There is some promising exploration of the CXCR1 axis involved in the aggressiveness of gastric cancer." (PMID 36831112, 2023). "In our ongoing study, we also have found that IL-8 can influence the biological behavior of gastric cancer (GC) by promoting the release of NETs through CXCR1/2." (PMID 34758877, 2021). "CXCR1/2 inhibitor Repertaxin enhanced chemotherapeutic efficacy of 5-fluorouracil in gastric cancer by attenuating cell proliferation, inducing apoptosis and suppressing malignant behavior." (PMID 33414786, 2020). "CXCR1 (C-X-C motif chemokine receptor 1): It has been reported to be strongly expressed in gastric carcinoma." (PMID 31616468, 2019). "High expression of CXCR1 identified a subgroup of TNM stage II gastric cancer patients who appeared to benefit from 5-FU based ACT." (PMID 27780937, 2017). "The knockdown of CXCR1 was reported to be able to prohibit the proliferation of cancer cells and even induce tumor cell apoptosis in gastric cancer." (PMID 27780937, 2017). "The expression of CXCR1 in human gastric cancer tissues was evaluated by means of immunohistochemistry." (PMID 27780937, 2017). "Next, so as to discover the prognostic capability of CXCR1 in resectable gastric cancer, we used Kaplan-Meier survival analysis to compare OS based on the expression of CXCR1." (PMID 27780937, 2017). "The purpose of our curret study is to discover the clinical prognostic significance of CXCR1 in resectable gastric cancer." (PMID 27780937, 2017). "In order to inspect the relation between CXCR1 immunohistochemical intensity and gastric cancer progression, first of all we evaluated CXCR1 expression through IHC staining analysis in the total of 330 gastric cancer patients." (PMID 27780937, 2017). "In our current study, we planned to discover the clinical prognostic effect of CXCR1 on resectable gastric cancer patients." (PMID 27780937, 2017). "Combining CXCR1 expression with current TNM staging system could lead to better risk stratification and more accurate prognosis for gastric cancer patients." (PMID 27780937, 2017). "CXCR1 in gastric cancer was identified as an independent adverse prognostic factor." (PMID 27780937, 2017). "Nevertheless, the exact role which CXCR1 plays in gastric cancer still remains unclear and needs further investigation." (PMID 27780937, 2017). "Combination of CXCR1 expression with present TNM staging system was able to give more precise prognostic information for gastric cancer patients, and might consequently help to identify the patients in need of a much more stringent postoperative follow-up." (PMID 27780937, 2017). "In conclusion, our study clarified that CXCR1 expression could predict unfavorable prognosis and be adopted as a novel prognosticator for resectable gastric cancer patients." (PMID 27780937, 2017). "Incorporating CXCR1 expression into current TNM staging system could generate a novel clinical predictive model for gastric cancer, showing better prognostic accuracy with respect to patients’ OS." (PMID 27780937, 2017).
gastric cancer (continued). "The results displayed above demonstrated that the incorporation of CXCR1 into TNM staging system could generate a more precise prognostic model for the prognosis of resectable gastric cancer patients." (PMID 27780937, 2017). "Next, we aimed to investigate whether the combination of CXCR1 expession with the present TNM stage would improve the predictive accuracy for gastric cancer." (PMID 27780937, 2017). "Furthermore, the findings shed light on individual chemotherapy treatment in gastric cancer patients on the basis of CXCR1 expression, because patients with CXCR1-high tumors tended to have improved outcomes after receiving 5-FU based ACT, especially for the patients with TNM II disease." (PMID 27780937, 2017). "Consequently, high expression of CXCR1 might serve as an adverse prognostic factor for TNM II or III resectable gastric cancer." (PMID 27780937, 2017). "Consequently, our findings suggest that CXCR1 expression could be a reliable independent adverse molecular prognosticator for patients with resectable gastric cancer." (PMID 27780937, 2017). "One group found that high expression of CXCR1 in Tumor, Nodes, Metastasis (TNM) Stage II and III gastric cancer is a poor prognostic factor." (PMID 36831112, 2023). "Since noticing the potential role of CXCL8, CXCR1, and CXCR2, more scientists have explored their relationship with gastric cancer." (PMID 36831112, 2023). "Thus, the detection of CXCR1 expression in gastric cancer tissues might also assist clinicians to give more suitable clinical treatment and postoperative management strategy to the gastric cancer patients." (PMID 27780937, 2017). "For these reasons, our results suggest that FPR2, CARD14, CXCR2, EFNA2, CXCR1, AQP9 TRIP13, along with GHRL and KLK11, could be used as promising biomarkers for gastric cancer diagnosis or prognostic evaluation." (PMID 34012923, 2021). "Similarly in gastric cancer, neutrophils like cells expressed CXCL8 and induced EMT through CXCR1/CXCR2 receptors and CXCL16 produced by MSCs induces proliferation and migration of tumor cells." (PMID 33414786, 2020). "Although there have been some studies on CXCR1/2 in several cancer types and there have been a few reports on the role of CXCR1/2 in gastric carcinoma, to date, the significance of CXCR1/2 expression in gastric cancer progression has not been evaluated in detail." (PMID 23420470, 2013). "Consequently, CXCR1 expression could not stratify the overall survival of patients with resectable, TNM I gastric cancer as was shown in our findings." (PMID 27780937, 2017).
diabetes (13 papers, 2015 to 2025). "In this scenario, the CXCR1/2 pathway is emerging as implicated in several phases of diabetes development and progression." (PMID 39627194, 2024). "The interplay between the CXCR1/2 pathway and TNF-α is pivotal in understanding the mechanisms underlying IR and inflammation in diabetes." (PMID 39627194, 2024). "The early blockade of neutrophil chemotaxis into the islets of neonatal NOD mice using the CXCR1/2 SB225002 antagonist decreased diabetes incidence in NOD mice." (PMID 26230114, 2015). "Similarly, treating zMIR fish and Akita mice with a CXCR1/2 antagonist also suppresses diabetes development." (PMID 36001973, 2022). "Blocking neutrophil recruitment by CXCR1/2 antagonists dampens or reverses diabetes development." (PMID 36001973, 2022). "A relationship between CXCR1/2 chemokine receptors and the advancement of insulitis and diabetes in mice has been previously established, demonstrating that transient CXCR1/2 inhibition inhibits inflammation-mediated islet impairment in the mild streptozotocin models." (PMID 34571976, 2021). "Thus, the attenuation of IL-8 action, which acts through CXCR1/2, may be proposed as a target for the prevention or treatment of diabetes and its related disorders." (PMID 34571976, 2021). "We speculate that low Cxcr1 expression in NOD mouse contributes to diabetes pathogenesis." (PMID 26230114, 2015). "In our study, we found lower amounts of Cxcr1 mRNA in neutrophils and CD4+ lymphocytes isolated from NOD mice as compared to diabetes-resistant mice." (PMID 26230114, 2015). "Therefore, we hypothesized that the activation of CXCR1/2 may have a detrimental role in the insulin sensitivity, thus inducing resistance and its inhibition may have positive effects on improving insulin sensitivity and preventing or treating metabolic disorders such as diabetes mellitus." (PMID 39627194, 2024). "Neutrophils expressing CXCR1/2 can be recruited to the pancreas by murine β cells, and macrophages produce C-X-C motif ligand 2 (CXCL2) in autoimmune diabetes, which plays a vital role in the early stages of diabetes." (PMID 32377527, 2020). "Thus, the interaction between CXCR1/2 and TNF-α signaling pathways may contribute to the dysregulation of insulin sensitivity and the pathogenesis of diabetes." (PMID 39627194, 2024). "Ladarixin, an allosteric non-competitive CXCR1 and CXCR2 antagonist, delayed the onset of diabetes and improved glycemic control when administered following multiple low-dose STZ injections in C57BL/6 mice." (PMID 40718478, 2025). "In addition, a related compound, ladarixin, which has equivalent selectivity for CXCR1 and CXCR2 and is orally bioavailable, can delay diabetes onset in non-obese diabetic mice and is currently in a phase 2 clinical trial for new-onset diabetes type 1 (NCT02814838, ClinicalTrials.gov)." (PMID 41176546, 2025).
mastitis (12 papers, 2010 to 2025). Inflammation of breast tissue during lactation or postpartum due to an obstructed duct or infection. "Many mastitis associated genes like complement C5 (C5) and chemokine (C-X-C motif) receptor 1 (CXCR1), are reported to be conserved as high as up to 99% sequence similarity." (PMID 34222390, 2021). "Because of the important function of CXCR1 in the innate immunity of the mammary gland and a quantitative trait locus for clinical mastitis in this region of the bovine genome, CXCR1 polymorphisms form interesting study objects." (PMID 25944115, 2015). "Previous research indicated polymorphism c.980A > G in the CXCR1 gene to influence milk neutrophils and mastitis resistance." (PMID 25895496, 2015). "The CC genotype of CXCR1-777 associates with impaired neutrophil migration, impaired reactive oxygen species production in vitro and increased subclinical mastitis in vivo." (PMID 21054834, 2010). "Based on published research, it can be concluded that CXCR1 and its reported polymorphisms might be considered potential markers for mastitis resistance/susceptibility in dairy cattle." (PMID 36911690, 2023). "In addition, earlier studies have reported that a non-synonymous mutation, c.365C > T, located in exon II of the CXCR1 gene is associated with susceptibility to mastitis in different breeds of cattle." (PMID 35723402, 2022). "CXCR1 (chemokine (C-X-C motif) receptor 1), identified as a hub gene, is a protein-encoding gene for major pro-inflammatory cytokine receptors that is introduced as a potential genetic marker for resistance to mastitis in dairy cows." (PMID 35723402, 2022). "The genes NOD2, CXCR1, SPP1 and LF, which are implicated in resistance to occult mastitis, were genotyped utilizing the efficient and cost-effective Kompetitive Allele-Specific PCR (KASP) technology." (PMID 40428307, 2025). "The identification of IL-1α, IL-6, and CXCR1 as key modulators offers promising avenues for the development of molecular biomarkers and genetic selection strategies aimed at enhancing mastitis resistance in dairy herds." (PMID 40453956, 2025). "A study found that the CXCR1+472 variant was significantly linked to milk SCS and increases the susceptibility to S. aureus-mastitis in dairy cattle." (PMID 36911690, 2023). "Among these, seven genes (CXCR1, HCK, IL1RN, MMP9, S100A9, GRO1, and SOCS3) were identified as the hub genes and these can be explored as potential candidate genes for mastitis susceptibility and resistance." (PMID 35723402, 2022). "Associations between polymorphisms in the bovine CXCR1 gene, encoding the chemokine (C-X-C motif) receptor 1 (IL8RA), and neutrophil traits and mastitis have been described." (PMID 25944115, 2015). "Interleukin-8 receptor α (IL-8RA), coded by the chemokine receptor CXCR1, is located on the surface of neutrophil and connects the pro-inflammatory IL-8 with high affinity and is, therefore, targeted widely as a potential marker in mastitis control research." (PMID 36911690, 2023). "Similarly, another study also reported the significant association of SNP c.337A>G and c.365C>T in CXCR1 with the milk SCC, suggesting their role in the host response against mastitis." (PMID 36911690, 2023). "The role of CXCR1 has been well-studied in mastitis resistance in dairy cattle research." (PMID 36911690, 2023). "Among these, seven genes—CXCR1, HCK, IL1RN, MMP9, S100A9, GRO1, and SOCS3—were identified as the hub genes (highly connected genes) for mastitis susceptibility and resistance, and were subjected to protein-protein interaction (PPI) network and gene regulatory network construction." (PMID 35723402, 2022). "In addition, CpG sites in the promoter region of bovine CXCR1 were found to potentially affect its gene expression during S. aureus-induced mastitis." (PMID 33193625, 2020).
mastitis (continued). "Associations between genotypes (mainly SNPs) and mastitis-associated phenotypes (mainly SCS) have been demonstrated for 157 candidate genes in ruminants, several of which have been reported in multiple independent association studies (e.g., CXCL8, CXCR1, TLR4)." (PMID 36759924, 2023). "Some of the genes differentially regulated during mastitis have been reported in multiple independent expression studies (e.g., CXCL8, CXCR1, LTF, TLR4)." (PMID 36759924, 2023). "The most important overexpressed genes in cows with mastitis were GRO1, CXCR1, SOCS3, S100A9, MMP9, HCK, and IL1RN, which were hub genes (highly connected genes) involved in mastitis in this study." (PMID 35723402, 2022). "CXCR1 and CXCR2 have been considered as prospective genetic markers for mastitis resistance in dairy cows." (PMID 33535694, 2021). "In the case of the cytokine–cytokine-receptor interaction pathway, other genes, such as CD40, IL1RN, CXCR1, TNFRSF6B, and CCL19, were found to be involved in mastitis defense or immune response, as all these genes were upregulated in the mastitic cows based on their FC values." (PMID 35723402, 2022).
viral infection (10 papers, 2009 to 2025). "CXCR1 has recently been shown to be upregulated on hepatocytes in response to liver injury and CXCR1 positive CD8+ T cells responding to CXCL8 have been detected in different viral infections." (PMID 24646914, 2014). "This suggests the possibility that CXCR1 may have antiviral function by enhancing recruitment of immune cells to the virus infection site." (PMID 32986779, 2020). "While our study primarily focuses on transcriptomic data, in vivo evidence from other disease models supports the modulation of CXCR1 and IL18RAP genes during viral infections." (PMID 40124360, 2025). "CXCL8 could mediate productive infection of HIV-1 in cells via receptors CXCR1 and CXCR2 and also could be induced by Porcine epidemic diarrhea virus nsp4 which in turn inhibited virus infection." (PMID 35937300, 2022). "Clinical trials using CXCR1 and CXCR2 inhibitors revealed that they are successful in treating patients with chronic diseases (e.g., COPD), whereas their use can be detrimental in patients with viral infection." (PMID 32733442, 2020).
osteosarcoma (9 papers, 2018 to 2025). A usually aggressive malignant bone-forming mesenchymal neoplasm, predominantly affecting adolescents and young adults. "Another study reports that miR-761 can impede osteosarcoma cell growth and invasion partly via targeting CXCR1." (PMID 34516330, 2021). "Mesenchymal stem cell-derived CXCL8 promotes osteosarcoma cell anoikis resistance and pulmonary metastasis through CXCR1/Akt signaling." (PMID 35011369, 2021). "IL-8 can activate the chemokine receptor CXCR1 (C-X-C Motif Chemokine Receptor 1) and can lead to anoikis resistance of osteosarcoma cells and progression of pulmonary metastasis." (PMID 34830463, 2021). "CXCR1 gene knockdown improves the sensitivity of human osteosarcoma to cisplatin both in vivo and in vitro." (PMID 35011369, 2021). "As suggested by Du, CXCR1 expressed on osteosarcoma cells maintained the viability and metastasis of cancer stem cells via the IL-8/CXCR1/Akt pathway." (PMID 31747966, 2019).